GATA3 (GATA binding protein 3)
Diseases named in the same sentence as GATA3 in open-access papers (continued):
Sharing a sentence is not in itself a finding about the gene and the disease.
experimental autoimmune encephalomyelitis (7 papers, 2013 to 2025). An autoimmune demyelinating disease of the central nervous system that is produced experimentally in animals by the injection of homogenized brain or spinal cord in Freund's adjuvant. "As Th2 cells, stabilized by GATA3 activity, provide neuroprotection for MS disease, then GATA3 overexpression, stimulating a Th2 response, can reduce disease severity and delay the onset of experimental autoimmune encephalomyelitis (EAE) in an MS animal model." (PMID 39768217, 2024). "E2 promotes Th2 activity: E2 at pregnancy levels of concentration enhanced the expression of GATA binding protein 3 (GATA3) and IL-4 in ovariectomized experimental autoimmune encephalomyelitis (EAE) model mice." (PMID 31547021, 2019). "DHA diminished GATA-3 expression in a mouse model of experimental autoimmune encephalomyelitis, in accordance with our data." (PMID 24040386, 2013). "In this study, lower RORγT and higher GATA-3 transcription factor expression levels in CD4+ cells were also detected in experimental autoimmune encephalomyelitis mice treated with hMSCs, which suggests that the Th17 phenotype is restrained while the Th2 subset is favored by the treatment with hMSCs." (PMID 30254638, 2018). "T-bet+ Gata-3+ CD4+ T cells can occur in parasite infection, and T-bet/RORγt double-positive cells have been seen in murine experimental autoimmune encephalomyelitis models." (PMID 34216540, 2021).
glioblastoma (7 papers, 2018 to 2025). The most malignant astrocytic tumor (WHO grade IV). "Additionally, previous studies have stated that CD276 (B7-H3), GATA3, and galectin-3 enable prognosis prediction in glioblastoma, and that correlation between lower balance of Th2 helper T-cells and lower expression of PD-L1/PD-1 axis genes also estimate prognosis in glioblastoma." (PMID 39707577, 2024). "Notably, genes such as CD276 (B7-H3), GATA3, and LGALS3 (galectin-3) have been shown to play significant roles in glioblastoma prognosis." (PMID 39068393, 2024). "We conducted expression profiling of CD274 (PD-L1), GATA3, IFNG, IL12R, IL12RB2, IL4, PDCD1 (PD-1), PDCD1LG2 (PD-L2), and TBX21 (T-bet) using data of 158 glioblastoma multiforme (GBM) patients with clinical information available at The Cancer Genome Atlas." (PMID 29721184, 2018).
hearing loss (7 papers, 2013 to 2025). "Since haploinsufficiency of Gata3 causes HDR syndrome, characterized by moderate to severe hearing impairment with loss of otoacoustic emission (OAE), the expression level of Gata3 is likely important in the development of the OHC." (PMID 28118374, 2017).
invasive lobular carcinoma (7 papers, 2021 to 2026). "Literature synthesis identified invasive lobular carcinoma as the predominant histology (57.14%), abdominal pain as the most common symptom (54.29%), and highlighted the diagnostic utility of immunohistochemical markers-particularly GATA3 (positive in 71.43% of tested cases)." (PMID 42078805, 2026). "An immunohistochemical panel consisting of estrogen receptor (ER), progesterone receptor (PR), gross cystic disease fluid protein (GCDFP-15), mammoglobin, and GATA3 can be useful in differentiating invasive lobular breast carcinoma." (PMID 34514560, 2021). "In this case, the immunohistochemistry of gastric metastasis was ER (90%), PR (-), Ki67 (2%), GATA3 ( +), CK (AE1/AE3) ( +), CK7 ( +), and CK20 (-), suggesting that the tumor originated from the breast and was considered as gastric metastasis of invasive lobular carcinoma of the breast." (PMID 36966290, 2023). "Histopathological examination of the ovarian masses demonstrated features characteristic of invasive lobular carcinoma of breast origin, confirmed by immunohistochemical staining positive for CKAE1/AE3, GATA-3 and GCDFP-15 and negative for markers of primary ovarian and gastrointestinal tumors." (PMID 41332036, 2025).
lobular carcinomas (7 papers, 2017 to 2026). "The histopathologic analysis disclosed mild chronic inflammatory infiltrate with thickened fibrous tissue and moderately differentiated lobular carcinoma cells, positive for GATA3 and CK7 markers, with 100% of tumor nuclei expressing estrogen receptors (ER+)." (PMID 38322413, 2024). "GATA-3, a pivotal transcription factor in breast epithelial differentiation, exhibits over 90% expression in primary and metastatic ductal and lobular carcinomas." (PMID 39022491, 2024). "The malignant cells were positive for p120 (cytoplasmic) and GATA3 and negative for estrogen receptor, progesterone receptor, human epidermal growth factor receptor 2, E-cadherin, gross cystic disease fluid protein 15 and mammaglobin, which indicated a lobular carcinoma phenotype of the breast." (PMID 28693516, 2017).
sarcoma (7 papers, 2013 to 2025). A usually aggressive malignant neoplasm of the soft tissue or bone. "Our case demonstrated a malignant GATA3+ spindle cell neoplasm on antemortem liver biopsy, raising the differential diagnosis of sarcomatoid carcinoma and high‐grade sarcoma." (PMID 40691018, 2025). "On the other hand, cells with GATA3 expression appeared to be few in different immune compartments from sarcoma bearing NLGP-treated mice." (PMID 23326300, 2013). "While reported at lower rates, GATA3 may be expressed in high‐grade sarcomas such as synovial sarcoma, leiomyosarcoma and malignant peripheral nerve sheath tumour." (PMID 40691018, 2025). "Ectopic expression of GATA3 in Th1 cells may also explain the failure to restore Th1 differentiation, thus reducing Th1 immune response in sarcomas." (PMID 36005179, 2022). "Gene expression analysis showed five genes (homeobox A10 (HOXA10), GATA binding protein 3 (GATA3), prostaglandin D2 receptor 2 (PTGDR2), thymocyte selection associated high mobility group box (TOX), and C-C motif chemokine receptor 3 (CCR3)) were dysregulated (p < 0.05) in sarcoma patients." (PMID 36005179, 2022). "The reduced GATA3 expression in our study may explain the lower expression of GATA3 on Th1 cells rather than on Th2 cells, which is evident with reduced IFN-γ production in sarcoma patients." (PMID 36005179, 2022).
atopic dermatitis (6 papers, 2013 to 2018). "Atopic dermatitis increased the expression levels of T-bet and GATA-3 but decreased the expression of Foxp3 in BALB/c mouse, in an SOCS1-dependent manner." (PMID 30459600, 2018). "Our cell cultures experiments revealed that a downregulation in GATA3 by shRNA leads to a significant reduction of filaggrin mRNA under atopic dermatitis-like conditions in keratinocytes." (PMID 28928464, 2017). "This function has made GATA3 a promising therapeutic target in Th2 cell based diseases like atopic dermatitis and allergic asthma." (PMID 28928464, 2017). "It was shown elevated mRNA levels of SOCS-3 and GATA-3 are present in PBMC of patients with atopic dermatitis." (PMID 24138793, 2013). "Atopic dermatitis increased the expression levels of T-bet and GATA-3 [transcription factors of T-helper 1 (Th1) and T-helper 2 (Th2) cells, respectively] but decreased the expression of Foxp3, a transcription factor of regulatory T (Treg) cells, in an SOCS1-dependent manner." (PMID 30459600, 2018). "Moreover, by expanding the analysis to punch biopsies from atopic dermatitis lesions, we found a differing expression pattern of GATA3 in the epidermis of AD patients when compared to healthy controls." (PMID 28928464, 2017). "The samples of lesional skin from atopic dermatitis patients showed increased expression of GATA3 in the basal and suprabasal layers whereas the expression was reduced in the upper layers of stratum spinosum and stratum granulosum when compared to non-lesional skin and healthy controls." (PMID 28928464, 2017). "Thus, GATA3 may be of special importance for the establishment and maintenance of an intact epidermal barrier, especially in atopic dermatitis." (PMID 28928464, 2017).
cervical cancer (6 papers, 2014 to 2025). A primary or metastatic malignant neoplasm involving the cervix. "miR-205 directly targeted GATA3, and its overexpression enhanced cell viability, migration, and tube formation in cervical cancer cells." (PMID 41514651, 2025). "Importantly, restoring GATA3 expression counteracted the oncogenic effects of miR-205, indicating a functional miR-205/GATA3 regulatory axis that may influence cervical cancer progression." (PMID 41514651, 2025). "GATA3 and HER2 were markedly expressed in the patients with cervical cancer, and this expression was strongly correlated with the early detection of recurrent disease." (PMID 36768623, 2023). "In cervical cancer, miR-205 was found to be upregulated, while GATA3 was downregulated, suggesting a negative correlation." (PMID 41514651, 2025).
cholangiocarcinoma (6 papers, 2021 to 2025). A carcinoma that arises from the intrahepatic biliary tree (intrahepatic cholangiocarcinoma) or from the junction, or adjacent to the junction, of the right and left hepatic ducts (hilar cholangiocarcinoma). "Overall, GATA3 was positively correlated with the immune status of most cancers, such as uveal melanoma, colon adenocarcinoma, and cholangiocarcinoma." (PMID 35647011, 2022). "According to the documented literature and our data, the positivity of MGP, GATA3, and TRPS1 is extremely rare in other tumor types, such as cholangiocarcinoma and colorectal, gastric, and thyroid carcinomas." (PMID 36284362, 2022).
clear cell carcinoma (6 papers, 2021 to 2025). "GATA-binding protein 3, a transcription factor, is commonly expressed in various sweat gland carcinomas, such as clear cell adenocarcinoma and porocarcinoma, but its diagnostic value in differentiation is limited." (PMID 39624633, 2024). "The clear cell carcinoma lesion was GATA3 negative and HNF4α positive; however, the urothelial cancer lesion was GATA3 positive and HNF4α negative." (PMID 34136304, 2021). "GATA3 and TTF1 are usually negative in clear cell carcinomas." (PMID 33670088, 2021).
kidney tumors (6 papers, 2016 to 2025). "While GATA3 can aid in distinguishing specific renal tumor subtypes, its use should be limited to a panel of markers rather than as a sole diagnostic tool." (PMID 40860802, 2025). "Among renal tumors, the highest expression is observed in PRNRP and low-grade oncocytic tumors (LOTs), both of which shows 100% GATA3 positivity." (PMID 40860802, 2025). "Interestingly, another recently identified indolent renal neoplasm, papillary renal neoplasm of reverse polarity, has been consistently found to exhibit diffuse membranous staining for both L1CAM and GATA3." (PMID 40805143, 2025). "Although GATA3 expression in kidney tumors is not well documented, there appears to be a pattern of GATA3 expression in tumors believed to originate from the distal tubules and collecting ducts." (PMID 40860802, 2025). "Histochemistry showed TTF-1 was positive, CgA was paranuclear punctate positive, and the urothelial marker GATA3 was negative, which well proved that the source of the kidney tumor in this case was lung small cell carcinoma." (PMID 37161448, 2023).
metastasis (6 papers, 2017 to 2026). The spread or migration of cancer cells from one part of the body (where they first appeared) to another. "All 30 primary tumors stained positively for GATA-3, whereas metastases were positive in six of eight cases (5 of 7 for lymph nodes and the brain metastasis)." (PMID 29116378, 2018). "Moreover, several included studies mentioned a connection between expression of GATA3 with clinicopathological features; among them, four focused on the expression of ER, PR, Her-2 and nuclear grade, while three focused on tumor size and lymph node metastasis." (PMID 28394898, 2017).
parasite infection (6 papers, 2005 to 2024). "Stable Tbet+GATA3+ double positive CD4 T-cell populations were observed during parasitic infections and had decreased IFNγ production upon restimulation." (PMID 35186781, 2021). "Stable Tbet+GATA3+ double positive CD4 T-cell populations are produced during parasitic infections and have low IFNγ production upon restimulation." (PMID 35186781, 2021). "Thus, GATA-3 expression in macrophages may fulfil an important role, possibly in conjunction with the altered phenotype of these cells in chronic parasite infections." (PMID 15788098, 2005). "ILC2s are dependent on the transcription factors GATA-binding protein 3 (GATA3) and retinoic acid-related orphan receptor (ROR)α and produce classical type 2 cytokines such as interleukin (IL)-4, IL-5, and IL-13 in response to parasite infection and allergen exposure." (PMID 36032129, 2022). "After expulsion of the parasites, H. polygyrus–induced T-bet+GATA-3+ cells maintained GATA-3 expression similar to their T-bet− Th2 counterparts and constantly expressed T-bet at levels like the pool of T-bet+ Th1 effector/memory cells unrelated to the parasite infection." (PMID 23976880, 2013).
prostate tumors (6 papers, 2016 to 2025). "In Pten-deficient prostate tumors, the expression of GATA3 is gradually lost during its progression." (PMID 28599307, 2017). "GATA3 expression negatively correlated with DNA methylation at specific loci in a subset of prostate tumors from AA men (left panel: left top quadrant)." (PMID 38566104, 2024). "Regardless of race, GATA3 was significantly downregulated in prostate tumors compared to adjacent non-tumor tissues (P < 0.001)." (PMID 38566104, 2024).
salivary gland tumors (6 papers, 2017 to 2025). "One salivary gland tumor showed poorly cohesive large epithelioid cells with prominent background inflammation and expressed AR and GATA3, in line with a possible salivary duct carcinoma variant." (PMID 39387893, 2025). "Needless to say, GATA3 can also be positive in salivary gland tumors." (PMID 40025593, 2025). "Other tumors with a less frequent expression of GATA3 include salivary gland tumors, malignant mesotheliomas, pancreatic adenocarcinomas, skin squamous cell carcinomas, skin adnexal tumors, renal oncocytomas, chromophobe renal cell carcinomas, and yolk sac tumors." (PMID 28693610, 2017).
Stroke (6 papers, 2016 to 2025). Sudden impairment of blood flow to a part of the brain due to occlusion or rupture of an artery to the brain. "Individuals with chronic Chagas cardiomyopathy at low stroke risk show increased expression of GATA-3, Foxp-3, and IL-1034." (PMID 39907396, 2025). "In this study, we demonstrated that patients with low stroke risk have increased mRNA expression of GATA-3, Foxp3, PU.1, AHR, IL-9, IL-22 and IL-10." (PMID 27115869, 2016). "We observed that low stroke risk patients exhibited higher GATA-3, Foxp3, PU.1, AHR, IL-9, IL-10 and IL-22 expression levels than did patients with high stroke risk." (PMID 27115869, 2016). "Notably, reduced expression of transcription factors (GATA-3, FoxP3), cytokine IL-10, and elevated mRNA expression of IFN-γ, TNF-α, and inducible nitric oxide synthase (iNOS) have been observed to increase the risk of death from stroke in these patients patients." (PMID 39217407, 2024). "Using flow cytometry, we analyzed the percentage of CD4 + T-bet + T cells and CD4 + GATA3 + T cells from peripheral blood of ATHS and CES patients (2,4 and 7 days after stroke onset)." (PMID 36180482, 2022). "Importantly, GWAS have associated variants of several of the gene targets of miR-24-3p;FAF1, GATA3, MMP14, NOS3 and PTPRF with stroke." (PMID 36613546, 2022).
B-cell lymphomas (5 papers, 2016 to 2025). "We already mentioned that, analog to PU.1, also systematic imbalance of the expression states of GATA3 can lead to tissue transformation and that loss of GATA3 has been found to induce B cell lymphoma." (PMID 28513551, 2017). "We found that heterozygous germline deletion of Gata3 in p18 deficient background led to development of B cell lymphomas." (PMID 27588406, 2016). "Furthermore, we discovered that haploid loss of Gata3 in p18 deficient mice led to the development of B cell lymphomas that were capable of rapidly regenerating tumors when transplanted into immunocompromised mice." (PMID 27588406, 2016). "However, it remains elusive how the loss of function of GATA3 promotes B cell development and induces B cell lymphomas." (PMID 27588406, 2016). "GATA3 is T-cell transcription factor required for early T-cell development and its expression in B-cell lymphoma including CHL is exceptional." (PMID 31831043, 2019). "Therapeutic gains have languished behind those achieved for the more common B-cell lymphomas, as few complete and durable responses are achieved with available targeted agents, particularly among those for which a GATA-3 dependent transcriptional program is oncogenic." (PMID 41309546, 2025). "Notably, Gata3 cooperates with p18 to repress B cell lymphomas, suggesting that Gata3 functions as a tumor suppressor in B cells in addition to its role as a tumor promoter in T cells." (PMID 27588406, 2016). "We demonstrated that haploid loss of Gata3 in mice enhances B cell differentiation at young age and leads to B cell lymphomas in aged mice in the absence of a cell cycle inhibitor, p18." (PMID 27588406, 2016). "Notably, GATA3 is undetectable in the majority of B-cell lymphomas including the nodular lymphocyte predominance type of Hodgkin lymphomas and various B cell non-Hodgkin lymphomas whereas it is aberrantly expressed in some of the Hodgkin and Reed/Sternberg cells (HRS) cells." (PMID 27588406, 2016).
carcinosarcoma (5 papers, 2021 to 2024). A malignant tumor composed of a mixture of carcinomatous and sarcomatous elements. "All patients exhibited endometrioid histology, except for the carcinosarcoma patient (P13), and all exhibited preoperative overexpression of PanCK, GATA3, HE4, and HER2." (PMID 36768623, 2023). "The expression of GATA-3 in the tumour biopsy before neoadjuvant treatment indicated urothelial origin of the carcinosarcoma." (PMID 33727576, 2021). "GATA3 was expressed across histotypes (16 cases total; 10 endometrioid (62.5%), 3 serous (18.8%), 2 carcinosarcoma (12.5%), and 1 clear cell (6.25%))." (PMID 33986807, 2021).
chromophobe renal cell carcinoma (5 papers, 2014 to 2025). Chromophobe renal cell carcinoma is a rare subtype of renal cell carcinoma, originating from the intercalating cells of the collecting ducts and macroscopically manifesting as a well-circumscribed, highly lobulated, solid tumor that is usually diagnosed at an early stage. "In the kidney, except for chromophobe renal cell carcinoma, there is a low rate of GATA3 positivity, which may be helpful for differentiation." (PMID 37629741, 2023). "Chromophobe renal cell carcinoma (ChRCC), a rarely encountered tumour in the metastatic setting, is GATA3 positive in up to 50% of cases including clinically aggressive tumours with sarcomatoid differentiation." (PMID 40691018, 2025).